UBQLNL (ubiquilin like)
Synonyms: MGC20470; MGC26958
Tractability: No criterion of Open Targets' tractability assessment is met for any kind of drug.
Gene: Protein-coding gene on chromosome 11 (5,514,393 to 5,518,431, reverse strand). Ensembl gene ENSG00000175518.
Gene Ontology:
Molecular function: protein binding
Biological process: ubiquitin-dependent protein catabolic process
Genetic constraint (gnomAD): Missense variants: 563 observed, 576.69 expected, observed/expected ratio (o/e) 0.98, 90% interval 0.91 to 1.05. Synonymous variants: 215 observed, 211.33 expected, observed/expected ratio (o/e) 1.02, 90% interval 0.91 to 1.14.
Homologues: Orthologues: rabbit UBQLNL (73% identical), macaque UBQLNL (65% identical), rat Ubqlnl (59% identical), mouse Ubqlnl (59% identical), pig UBQLNL (58% identical), Drosophila melanogaster CG31528 (12% identical). Paralogues in human: UBQLN1 (34% identical), UBQLN2 (32% identical), UBQLN4 (30% identical), UBQLN3 (25% identical), UBL7 (9% identical).
Diseases named in the same sentence as UBQLNL in open-access papers:
UBQLNL is named in the same sentence as 2 diseases in open-access papers, as found by Europe PMC text mining. Sharing a sentence is not in itself a finding about the gene and the disease. The quoted sentences say what the papers report.
COVID-19 (1 paper, 2022). A disease caused by infection with severe acute respiratory syndrome coronavirus 2. "Ubiquilin like (UBQLNL) that encodes for a regulator of proteostasis and showed enhanced expression in seriously ill COVID-19 patients." (PMID 36143338, 2022).
cancer (1 paper, 2021). A tumor composed of atypical neoplastic, often pleomorphic cells that invade other tissues. "The heatmap indicated that UBQLN4 was positively related to UBQLN1 and UBQLN2 in most cancers with statistical significance, while few correlations were found between UBQLN4 and the remaining two members (UBQLN3 and UBQLNL)." (PMID 34539785, 2021).